LINC01436 (long independently transcribed non-coding RNA 1436)
Synonyms: AP000688.8
Gene: Long non-coding RNA gene on chromosome 21 (36,005,131 to 36,008,300, forward strand). Ensembl gene ENSG00000231106.
Diseases named in the same sentence as LINC01436 in open-access papers:
LINC01436 is named in the same sentence as 7 diseases in open-access papers, as found by Europe PMC text mining. Sharing a sentence is not in itself a finding about the gene and the disease. The quoted sentences say what the papers report.
gastric cancer (4 papers, 2020 to 2024). A primary or metastatic malignant neoplasm involving the stomach. "The higher expression of linc01436 was observed in tumor tissues of gastric cancer patients and was associated with a poor survival in gastric cancer cases." (PMID 35928868, 2022). "LINC01436 has been shown to be involved in gastric cancer cell proliferation, apoptosis, metastasis, and radio resistance through upregulation of MAPK1 and FBOX11 via sponging and epigenetically silencing miR-585." (PMID 38279317, 2024). "Emerging evidence has revealed that linc01436 plays an oncogenic role in gastric cancer progression." (PMID 35928868, 2022). "It has been reported that LINC01436 can promote cell growth of non-small cell lung cancer and gastric cancer." (PMID 34285140, 2021). "Recent studies showed that some non-coding RNAs, such as Linc00483, Linc00460, and Linc01436, adsorbed miR-30a-3p and weakened the tumor-suppressive effects in gastric cancer, nasopharyngeal carcinoma, and non-small cell lung cancer, respectively." (PMID 32899691, 2020). "Similarly, linc01436 triggered gastric cancer progression through modulation of miR-513a-5p and apurinic/apyrimidinic endodeoxyribonuclease 1 (APE1)." (PMID 35928868, 2022). "Mechanistically, miR-585 can bind to linc01463 and FBXO11, suggesting that linc01436 sponges miR-585 and inhibit it, leading to indirect promotion of FBXO11 expression in gastric cancer." (PMID 35928868, 2022). "Moreover, using in vitro experiments, knockdown of linc01436 retarded metastasis and blocked proliferation in BGC823 gastric cancer cells, while increased linc01436 promoted metastasis and proliferative activity in AGS gastric cancer cells." (PMID 35928868, 2022).
non-small cell lung carcinoma (4 papers, 2019 to 2025). A group of at least three distinct histological types of lung cancer, including non-small cell squamous cell carcinoma, adenocarcinoma, and large cell carcinoma. "Gain‐ and loss‐of‐function studies revealed that LINC01436 acted as a proto‐oncogene by promoting lung cancer cell growth, migration and invasion in vitro." (PMID 30614188, 2019). "We next investigated the biological mechanism by which LINC01436 contributed to lung cancer progression." (PMID 30614188, 2019). "Here, we identified a novel up‐regulated lncRNA, LINC01436 (RefSeq: NR_110419.1), in non‐small cell lung cancer (NSCLC)." (PMID 30614188, 2019). "Further analysis showed that only miR‐30a‐3p was significantly negatively correlated with LINC01436 expression (r = −0.729, P = 0.017), suggesting that LINC01436 may serve as a sponge for miR‐30a‐3p in lung cancer." (PMID 30614188, 2019). "Our study showed LINC01436 acts as a ceRNA to regulate EPAS1 by sponging miR‐30a‐3p in lung cancer." (PMID 30614188, 2019). "In non-small cell lung cancer (NSCLC), LINC01436 functions as an oncogene by sequestering miR-30a-3p and is regulated by E2F6 in response to hypoxia." (PMID 39940704, 2025). "Here, we demonstrated that LINC01436 regulated the expression of EPAS1 and its target genes in lung cancer cell lines, including angiogenesis (VEGFA) and metabolism reprogramming (GLUT1) genes." (PMID 30614188, 2019). "Interestingly, repression of E2F6 by hypoxia was also observed in lung cancer cells, and the inhibitory effect of E2F6 on LINC01436 expression was relieved under hypoxia." (PMID 30614188, 2019).
tumor (4 papers, 2018 to 2025). "In this study, we demonstrated that LINC01436, a long intergenic noncoding RNA, was significantly up‐regulated in NSCLC tumor tissues and the high expression of LINC01436 was associated with poor outcomes in NSCLC." (PMID 30614188, 2019). "LINC01436 expression levels were significantly up‐regulated in NSCLC tumor tissues compared with adjacent normal tissues (P < 0.05)." (PMID 30614188, 2019). "Additionally, rescue experiments demonstrated that miR‐30a‐3p restored the tumor‐promoting effects of LINC01436, indicating that LINC01436 exerted its function through miR‐30a‐3p in NSCLC." (PMID 30614188, 2019). "To further determine whether LINC01436 promotes tumorigenesis in vivo, we used subcutaneous xenograft tumor models to assess the growth of A549 cells stably transfected with LINC01436 or control vector in nude mice." (PMID 30614188, 2019). "Compared with the normal group, the expression levels of the most significant four lincRNAs (LINC01088, LINC01018, LINC01436 and LINC00243) were remarkably down-regulated in the tumor group, and the down-regulation of LINC01088 was the most marked." (PMID 29440672, 2018). "To validate this result, we investigated the LINC01436 expression levels in 100 paired NSCLC tumor and adjacent normal lung tissues using qRT‐PCR." (PMID 30614188, 2019).
cancer (3 papers, 2019 to 2021). A tumor composed of atypical neoplastic, often pleomorphic cells that invade other tissues. "These genes were involved in critical steps of phenotype changes in cancer progression, underlining the impact of LINC01436 in lung tumorigenesis." (PMID 30614188, 2019). "LINC01436 advances cancer growth and metastasis in vivo, and LINC01436 can exhibit its function by sponging miR-30a-3p that directly regulates HIF-2α (also known as endothelial PAS domain-containing protein 1 (EPAS1))." (PMID 34298879, 2021). "Our results suggest that LINC01436 could play important roles in hypoxia‐regulated cancer progression, and may be a potential biomarker in prognosis and a therapeutic target for NSCLC." (PMID 30614188, 2019). "LINC01436 and LINC00242 appear to render cancer cell to progression." (PMID 34285140, 2021).
LINC01436 also shares sentences with these, for which no sentence is quoted: fibroids (2 papers); lung carcinoma (1); nasopharyngeal carcinoma (1).